AR (androgen receptor)
Diseases named in the same sentence as AR in open-access papers (continued):
Sharing a sentence is not in itself a finding about the gene and the disease.
adenocarcinoma (continued). "Emerging studies indicate that the rise of t-NEPC prevalence is most likely a consequence of neuroendocrine transdifferentiation of adenocarcinoma under the selection pressure of anti-AR therapies." (PMID 29156689, 2017). "To date, the molecular mechanisms by which adenocarcinoma progresses into t-NEPC under anti-AR therapies remain to be fully elucidated." (PMID 29156689, 2017). "NEPC is generally reported to lack AR and NED results in a decrease/loss of AR in the adenocarcinoma." (PMID 27542219, 2016). "Androgen-deprivation therapy consisting of bicalutamide and LHRH analog has been repeatedly reported to be an effective treatment option for AR+ adenocarcinomas of the salivary glands." (PMID 25699235, 2015). "Since increased DEK expression was observed immediately after host castration, it is possible that DEK is negatively regulated by AR signaling in adenocarcinoma." (PMID 25544761, 2015). "Herein, we describe for the first time a case of a patient with an androgen receptor expressing adenocarcinoma of the lacrimal sac that had an impressive response to abiraterone." (PMID 25699235, 2015). "It has been reported in vitro that prostate cells expressing FAS and androgen receptor (another activator of the PI3K-Akt pathway) can form invasive adenocarcinomas in immunodeficient mice, however, cells that expressed only FAS did not." (PMID 26622804, 2015). "The predominant subtype in CRPC is AR-positive adenocarcinoma (CRPC-adeno), but approximately 10–17% of patients treated with ADT or anti-androgen therapy exhibit a neuroendocrine differentiation (NE) phenotype, and these tumors are classified as neuroendocrine prostate cancer (NEPC)." (PMID 39975592, 2025). "Therefore, we utilized the LTL331/331R PDX model, which faithfully recapitulates transdifferentiation from an AR-positive adenocarcinoma to castration-resistant NEPC." (PMID 40454483, 2025). "Notably, NEPC and AR-positive adenocarcinoma cells exhibit highly similar genomic features, suggesting that androgen receptor pathway inhibitor-induced NEPC is mainly driven by lineage plasticity." (PMID 40821114, 2025). "By delineating the molecular events driving the transition from androgen receptor (AR)-dependent adenocarcinoma to treatment-resistant NEPC, this work underscores the potential of targeting early and dormant phases of transdifferentiation to improve patient outcomes." (PMID 41142932, 2025). "Silencing REST in C4-2 (NE-/AR+) adenocarcinoma cells leads to induction of NE markers." (PMID 38777812, 2024). "Thus, loss of Pten in prostate epithelial cells leads to slow-growing and homogeneously AR+ adenocarcinoma whereas co-deletion of Pten and Rb1 drives formation of much more aggressive PCa that is heterogeneous in AR expression with many AR–/lo PCa cells." (PMID 39363904, 2024). "Recent studies indicated that the transdifferentiation of adenocarcinoma cells into treatment-emergent NEPC (t-NEPC) is a critical mechanism of drug resistance after treatment with the second generation AR antagonists, and NEPC cells share the common characteristics of PCSCs." (PMID 37563661, 2023). "In PCa, this may be particularly advantageous as AR-sensitive adenocarcinoma adapts to a “fuel switch,” as it lacks lipogenesis pathway stimulation following AD." (PMID 36724278, 2023). "However, many factors have been associated with the emergence and progression of neuroendocrine differentiation in adenocarcinomas including the downregulation of AR and/or AR-mediated signaling and upregulation of specific oncogenic signaling." (PMID 35447888, 2022).
adenocarcinoma (continued). "While the majority of CRPC remains AR-positive and presents an adenocarcinoma phenotype, more potent AR pathway inhibitor (ARPI) treatment often induced AR negative neuroendocrine prostate cancer (NEPC) or double-negative prostate tumours (DNPC) accounting for ~20% of CRPC." (PMID 35832549, 2022). "Furthermore, their transcriptomic profiles showed the highest degree of similarity with AR+ adenocarcinomas when compared to an external cohort of CRPC patient tumors (n = 98)." (PMID 36429059, 2022). "The majority of PCa is adenocarcinoma (ADPC) that express androgen receptor (AR)." (PMID 35184376, 2022). "We hypothesized that this state would likely appear to have neuroendocrine expression from the NEPC component, as well as preserved AR target gene expression from the adenocarcinoma component." (PMID 36317634, 2022). "In the context of PTEN loss, which suppresses AR and favors basal differentiation, ERG increases AR binding to chromatin and restores expression of the AR transcriptional output, thereby leading to the development of adenocarcinoma." (PMID 35267426, 2022). "In adenocarcinomas, our findings suggest therapeutic targeting of specific AR isoforms may be insufficient but support clinical inhibition of TGF-β and further characterization of cytotoxic cells." (PMID 33664492, 2021). "Long-term androgen deprivation could promote adenocarcinoma cells lose androgen receptor (AR) expression and eventually developed to NEC cells, which was called treatment-related NEPC (t-NEPC)." (PMID 34956090, 2021). "Another emerging cell type is double negative PCa (DNPC)(Group 1, 2→Group 4), which is negative for both AR and neuroendocrine markers and may represent an intermediate phenotype between AR expressing adenocarcinoma and the neuroendocrine phenotype." (PMID 33163409, 2020). "The use of potent AR signaling inhibitors could promote the transformation of adenocarcinoma in the CRPC state to T-NEPC in a clonal manner." (PMID 33598420, 2020). "However, pathological examination of the resected specimen revealed poorly differentiated adenocarcinoma that was positive for other prostate markers such as androgen receptor." (PMID 33263827, 2020). "However, our adenocarcinoma cases had hybrid features with both AR and neuroendocrine markers present and high PSA levels." (PMID 30337589, 2018). "We did not have access to outcome data of the atypical hybrid SCPCs in our dataset and were not aware of other hybrid SCPCs in the literature, however rare adenocarcinoma cases with aggressive progression and hybrid IHC co-expression of AR and chromogranin have been reported." (PMID 29132337, 2017). "As transdifferentiation occurs, the CRPC adenocarcinoma undergoes a loss of AR expression to become an AR negative NEPC." (PMID 27542219, 2016). "Actually, one paper proposed that, when the cytologic features of high grade adenocarcinoma with a variety of cell morphology are difficult to make an accurate diagnosis, immunostaining for AR and ER on cytologic smears would be very useful for the diagnosis of SDC." (PMID 22647549, 2012). "Orthotopic adenocarcinoma uniformly displayed strong nuclear labeling of AR." (PMID 22022528, 2011). "Whether increased expression of AR and androgen signaling in a high grade primary adenocarcinoma would be clinically beneficial or detrimental is a subject of debate." (PMID 19691856, 2009). "High-grade adenocarcinoma with focal neuroendocrine differentiation is a rare and aggressive variant characterized by heterogeneous biology, often associated with low or absent prostate-specific antigen (PSA) expression, visceral metastases, and partial androgen receptor (AR) independence." (PMID 40949061, 2025).
adenocarcinoma (continued). "Specifically, the pre-castrated LTL-331 PDX initially exhibited a classic adenocarcinoma phenotype and gradually transformed to the t-NEPC LTL-331R PDX after surgical castration, during the process EHF was notably depressed and positively associated with AR, and negatively with SYP and SOX2." (PMID 33414441, 2021). "Atypical NEPC potentially includes a hybrid subcategory exhibiting preserved AR-signaling and a non-neuronal subcategory with AR loss and high proliferation but without expression of neuroendocrine markers that may overlap with adenocarcinomas." (PMID 29132337, 2017). "However, transdifferentiation of the adenocarcinoma to NEPC appears to occur in stages where tumors with NE features may still have AR or express AR target genes." (PMID 27542219, 2016). "On histopathology, the scalp tumor demonstrated an immunohistochemical profile supportive of an adenocarcinoma (pankeratin+, CEA+) with neuroendocrine differentiation (synaptophysin+) and hormonal receptor positivity (ER+, PR+, androgen receptor positivity)." (PMID 41143220, 2025). "As one of the downstream genes of AR, KLK3 was also negatively stained in PGCA, suggesting that the elevation of PSA was derived from the coexisting adenocarcinoma." (PMID 40873563, 2025). "These AR-positive, SYP-positive tumors (often referred to as amphicrine, example shown SI Appendix) have adenocarcinoma histology and clinically behave differently than bona fide NEPC tumors." (PMID 38968122, 2024). "While some regions reacquired PRAD histological features (moderate-to-well-differentiated adenocarcinoma harboring KRT8 and AR expression), the predominant histology was high-grade ASCL1− NEPC with sarcomatoid-like features." (PMID 39394434, 2024). "For all intracranial metastases with high grade adenocarcinoma, immunohistochemical (IHC) staining for NKX3.1 and AR were strongly and diffusely positive." (PMID 37704749, 2023). "The glandular development and expression of luminal differentiation markers androgen receptor (AR) and prostate-specific antigen (PSA) identify most prostatic malignancies that are adenocarcinomas." (PMID 35627227, 2022). "In our study, we used the transgenic adenocarcinoma of the mouse prostate model (TRAMP mice), to identify regulators of primary resistance against androgen receptor inhibition." (PMID 35159020, 2022). "Pathology review and immunohistochemistry for phenotypic markers (AR, PSA, PSMA, ERG, chromogranin A, synaptophysin, and CD56) showed that 9 research-ready PDXs are adenocarcinoma, 7 are neuroendocrine, and 1 has mixed pathology." (PMID 34413304, 2021). "Organoids derived from all investigated PDXs displayed budding acinar and adenocarcinoma-like morphology, with the expression of the luminal markers CK8, PSA and AR." (PMID 33602919, 2021). "Adenocarcinoma foci were enriched with EMT genes, PRC2 complex target genes, and AR signaling/prostate developmental genes." (PMID 34099734, 2021). "Particularly, we searched for studies that compared adenocarcinoma with aggressive disease like small cell NEPC and focused on serine and one carbon metabolism, CPT1A and AR expression in clinical data." (PMID 33218188, 2020). "As there is clear evidence suggesting that NEPC cells can be derived from PCa adenocarcinoma cells, we are particularly interested in this transition in response to ADT or suppression of AR signaling." (PMID 31189930, 2019). "Since the discovery of AR expression in SDC and high-grade adenocarcinoma NOS, several studies have explored the efficacy of ADT." (PMID 31428578, 2019). "Recently, mixed forms between adenocarcinoma and neuroendocrine prostate cancer (NEPC) have emerged that are characterized by persistent androgen receptor (AR)-signalling and elevated chromogranin A (CgA) levels." (PMID 30337589, 2018). "Increased AR staining in PIN lesions was observed compared to normal prostate tissue (WT), but was partially lost in adenocarcinomas." (PMID 29212195, 2017).
adenocarcinoma (continued). "Transduction of Trop2+CD49fHi prostate epithelial cells with activated AKT, ERG, and androgen receptor (AR) induces HGPIN and low-grade adenocarcinoma lesions in grafts obtained from prostate recombination assays." (PMID 27711225, 2016). "For patients with adenocarcinoma and SDC we routinely perform androgen receptor staining and HER-2 testing." (PMID 31093341, 2016). "We performed IHC to measure the expression of PROX1 along with NCAM1, AR, and the AR target, PSA, using tissue sections from samples collected at multiple time points (i.e., pre-castration adenocarcinoma [LTL331], 12 weeks post-castration, and relapsed NEPC [LTL331R])." (PMID 40454483, 2025). "We first assessed the expression of NKX3.1 and the AR protein in a panel of non-transformed (benign) and AR-positive adenocarcinoma cell lines." (PMID 39858088, 2025). "These resistant subpopulations, often AR-negative or double-negative, display marked molecular and metabolic divergence from classical adenocarcinoma, including upregulation of glucose transporters and hexokinases that facilitate increased glycolytic activity." (PMID 40806607, 2025). "On immunohistochemical analysis, the adenocarcinoma cells showed diffuse strong immunopositivity for Keratin 7 while immunonegativity for EMA, Keratin 5/6, p63, p40, Androgen receptor (AR), gross cystic disease fluid protein 15 (GCDFP-15), Her2Neu, BerEp4, S100, SMA and calponin." (PMID 40822511, 2025). "This high-throughput approach revealed synergy between CDKI-73 and AZD5153 in 305R-Cx (AR-negative, neuroendocrine) organoids and an additive effect of these drugs in 201.1A-Cx (AR-positive, CRPC-adenocarcinoma) organoids, determined using the SynergyFinder Plus tool." (PMID 39117800, 2024). "Interestingly, CDK9 mRNA levels were significantly higher in castration-resistant neuroendocrine prostate cancer (NEPC) tumors, which exhibit AR-low/null/independent phenotypes, compared to the more common CRPC adenocarcinoma phenotype." (PMID 39117800, 2024). "Around 15–20% of CPRC adenocarcinomas eventually lose all AR dependence and undergo a transformation to AR-negative, poorly differentiated neuroendocrine PC (NEPC)." (PMID 38337427, 2024). "In contrast to TROP2, CEACAM5 displayed a negative correlation with AR in CRPC–adenocarcinoma and was expressed in all NEPC clusters, suggesting that CEACAM5 is an actionable target for non–AR–driven disease." (PMID 38645034, 2024). "TROP2 expression was enriched across all adenocarcinomas regardless of AR status, indicative of a broader lineage profile." (PMID 38645034, 2024). "These new models represent well-known CRPC phenotypes, including AR-driven (AR+) adenocarcinoma and AR-independent neuroendocrine-positive (NE+) or double-negative (AR–NE–) lineages." (PMID 37183816, 2023). "The CSPC cell line LNCaP represents adenocarcinoma, 22Rv1 cells express an AR splice variant, DU145 as well as PC3 cells are AR negative but express other steroid hormone receptors and different oncogenic signaling pathways are activated." (PMID 36994208, 2023). "On the contrary, AR expression as well as AR driven gene signature such as expression of KLK3, or Nkx3.1 decreased in C4-2BER and DKD (representing t-NEPC) cells as compared to adenocarcinoma C4-2B and C4-2 cells respectively." (PMID 38168280, 2023). "Depletion of the chromatin modulator DEK with siRNAs (small interfering RNAs) suppresses cell growth, migration and invasion of PC3 cells, an AR-negative adenocarcinoma cell line sometimes used as an NEPC model." (PMID 37761978, 2023). "One mechanism behind this process is the histologic transformation from adenocarcinoma to a poorly differentiated neuroendocrine (NE) carcinoma with absent or low AR expression levels." (PMID 37761978, 2023). "At the transcriptomic level, both PDXs and PDXOs resembled CRPC patient tumors with an AR+ adenocarcinoma phenotype and an absence of transcriptional features typical of neuroendocrine or mixed morphologies." (PMID 36429059, 2022).
adenocarcinoma (continued). "Since scRNA-seq identified clusters within adenocarcinoma, we also used it to examine PDX 287R, which has homogenous adenocarcinoma pathology and AR expression, and no staining of neuroendocrine markers." (PMID 34413304, 2021). "Thirty-four patients (97%) were androgen receptor positive with one patient having AR negative adenocarcinoma." (PMID 31428578, 2019). "In the transgenic adenocarcinoma of mouse prostate (TRAMP) model, IL23 secreted from MDSCs can activate the androgen receptor (AR) pathway, promoting cell survival and proliferation under androgen-deprived conditions, suggested a mechanism of MDSC-mediated resistance to castration." (PMID 31408948, 2019). "We next analyzed an FFPE exon array dataset from our institution (JHU-FFPE) profiling 16 primary SCPCs and 16 adenocarcinomas (predominantly Gleason 9), notable for inclusion of mixed cases, AR-positive SCPCs, PSA-positive SCPCs, and NE-marker negative SCPCs." (PMID 29132337, 2017). "Using GRP-R targeted Ga68-BAY86-7548, a BN-analogue, it is possible to follow expression of GRP-R in both the AR positive adenocarcinomas as well as the AR negative NEPC tumors." (PMID 27542219, 2016). "Using both PSMA and GRP-R imaging in the same patient, it would be possible to detect both the androgen regulated PSMA expression adenocarcinomas as well as progression to the PSMA/AR negative NEPC." (PMID 27542219, 2016). "Together, these results indicate that GRP-R is targetable (such as imaging and/or radiotherapy) for both of AR positive adenocarcinoma and AR negative NEPC." (PMID 27542219, 2016). "It is characterized by small neuroendocrine (NE)-like cells which typically express NE markers such as chromogranin A (CHGA) and synaptophysin (SYP) and do not express androgen receptor (AR) or adenocarcinoma markers, such as prostate-specific antigen (PSA)." (PMID 25544761, 2015). "NCI-H660 cells and some batches of PC3 cells express ERα, but are not ideal models because they lack AR and have a small cell rather than adenocarcinoma phenotype." (PMID 25436982, 2015). "NEPC cells are AR-negative and are thought to arise via ‘transdifferentiation’ from AR-positive adenocarcinoma cells." (PMID 25155515, 2014). "For example, in this case high-grade adenocarcinoma would be modified with the description of double negative CRPC referring to the lack of AR activity or neuroendocrine features; these features may only become apparent through molecular testing." (PMID 38907236, 2024). "Importantly, this post-castration increase in DEK expression is not observed in other adenocarcinoma models that give rise to AR-positive relapsed cancers." (PMID 37761978, 2023). "Interestingly, it has been shown that the neuroendocrine subtype is not entirely foreign to AR-positive cells and partly originates from AR-positive conventional adenocarcinoma through a transdifferentiation process." (PMID 37189723, 2023). "Genetically engineered mouse models carrying overexpression of both AR and Src, but not alone, in normal prostate epithelial cells, can induce poorly or non-differentiated adenocarcinoma, supporting co-activation of AR and Src is required for prostate tumourigenesis." (PMID 35832549, 2022).